IL1B (interleukin 1 beta)
Diseases named in the same sentence as IL1B in open-access papers (continued):
Sharing a sentence is not in itself a finding about the gene and the disease.
gout (continued). "Previous studies have suggested that the activation of NLRP3 inflammasome induced by MSU crystal can result in pyroptosis and secretion of interleukin (IL)-1β, exacerbating inflammatory damage and progression of gout." (PMID 36569930, 2022). "The critical roles of the NLRP3 inflammasome and IL-1β in gout pathology have been revealed, and a blocking strategy for these pathways has emerged as a promising new therapeutic for gout attack." (PMID 36387275, 2022). "Alternatively, IL-1α, IL-1β, and IL-18 drive pathology in a range of human diseases, such as gouty arthritis, autoinflammatory disease, or cytokine storm in systematic infectious diseases." (PMID 36551320, 2022). "We described our experience with refractory gout cases successfully treated with the Il-1β inhibitor anakinra in 10 patients attended in a tertiary referral hospital." (PMID 36714095, 2022). "In the last decade, trials of inflammation-modifying treatments, such as IL-1β inhibition, have been tested as a treatment for gout with successful outcomes." (PMID 35811965, 2022). "ELISA analysis showed that the gout group significantly up-regulated the levels of IL-1β, Caspase-1, IL-6 and TNF-α, and significantly decreased the levels of IL-10, which were induced by MSU (p < 0.05)." (PMID 36313318, 2022). "The expression levels of three pro-inflammatory cytokines (i.e., IL-1β, IL-6, and TNF-α) associated with gout were further investigated in serum." (PMID 35145506, 2022). "Subsequently, neutrophils predominate at the inflammatory site and represent a significant cell population contributor to the pathology of gout through the release of pro-inflammatory mediators, such as IL-1β, TNF-α, or NETs and proteases." (PMID 36496970, 2022). "Quercetin has been reported to show an anti-inflammatory effect in gouty arthritis caused by MSU, showing inhibition of IL-1β release at a concentration of 30 μM, with reports suggesting that this effect is related to inhibition of the NLRP3 inflammasome." (PMID 36234744, 2022). "Mechanistic, genetic, and biomarker studies establish a strong link between pathological inflammasome activation, leading to IL-1β and IL-18 secretion and the progression of RA and gout." (PMID 35629398, 2022). "IL-33 not only triggers macrophage to release IL-1β, enhancing inflammation and pain; in gouty arthritis, it but also modulates bone cancer pain by regulating IL-6 and IL-1β." (PMID 36287299, 2022). "At the onset of gouty arthritis, MSU is involved in caspase-1 activation, which causes the production of interleukin-1β (IL-1β) and interleukin-18 (IL-18), inducing proinflammatory responses." (PMID 36297105, 2022). "During the development of gout, resident macrophages are the primary sources of IL-1β secretion, which play a critical role in the recruitment and massive infiltration of neutrophils." (PMID 36496970, 2022). "Acetate was reported to mediate joint inflammation in a murine gout model via inflammasome assembly and IL-1β." (PMID 35402298, 2022). "The implication of IL-1β in the pathogenesis of gout has been confirmed by the successful treatment of patients with severe gout using IL-1β inhibition." (PMID 34997110, 2022). "While the mean reduction by anti–IL-1β was comparatively small, it is interesting to note that a small subset of RA and gout synovial fluids showed stronger decreases of CXCL1/5 secretion upon anti–IL-1β treatment." (PMID 35801586, 2022). "Previous studies have shown that miR-488 can inhibit the expression of proinflammatory cytokines in gouty arthritis by targeting the 3′-UTR of IL-1β." (PMID 35186188, 2022). "MSU crystal injection reproduces in rodents the inflammatory characteristics observed in gout patients, such as redness, articular edema, neutrophil migration, as well as increased levels of IL-1β." (PMID 36173505, 2022). "Anti-inflammatory agents, colchicine, NSAIDs, corticosteroids, and anti-IL-1β biologics, are widely applied for the treatment of gout flare." (PMID 36090056, 2022).
gout (continued). "It has been reported that the activity of neutrophil-derived proteases plays a more dominant role in the acute inflammation induced by IL-1β in the gout context, suggesting that caspase-1 plays a minor role." (PMID 36496970, 2022). "Direct inhibition of the NLRP3 inflammasome as an alternative approach to targeting IL-1β reduces the inflammatory response in gout." (PMID 36142890, 2022). "The main mechanism by which MSU crystals cause inflammation is through activating the NLRP3 inflammasome and therefore, blocking NLRP3 or IL-1β is an effective treatment for severe or refractory gout." (PMID 36225929, 2022). "Previous studies have shown that IL-6, IL-1β, and TNF-α were associated with inflammatory activity in patients with gout." (PMID 35145506, 2022). "Our data suggest that the leukocytes of gout patients respond differentially to hyperuricemia and its comorbidities and increase the gene expression of ABCG2 and IL-1β compared to normouricemic and non-gout controls." (PMID 35505381, 2022). "We also scanned for the available literature by performing and presenting a scoping review, in which 551 gout patients treated with anti-IL1β were described." (PMID 36714095, 2022). "A previous study has demonstrated that acetate acid mediated joint inflammation in a murine gout model through inflammasome assembly and IL-1β production that is partially FFAR2 dependent." (PMID 35684581, 2022). "The results of RT-qPCR showed that the expressions of CCL7, CSF2RB and IL-1β were significantly up-regulated in the gout group compared with the control group (p < 0.05)." (PMID 36313318, 2022). "Although IL-1β production occurs in many inflammatory conditions, gout inflammation is unique because it is primarily driven by IL-1β." (PMID 35726318, 2022). "The cytokine IL-1β participation in the response to MSUs in gout attack has long been known, but little is known about its effect on ABCG2 and its interaction with other urate transporters." (PMID 35505381, 2022). "IL-1β is the main proinflammatory cytokine in initiating gout; however, the IL-1β-mediated inflammatory response is also critical in resolving infections to some extent, contributing to the body’s timely response to danger and self-recovery." (PMID 36052144, 2022). "IL-1β is believed to be a critical proinflammatory cytokine in the pathogenesis of gout, and exerts a wide range of systemic and local effects." (PMID 35154099, 2022). "The major role of IL-1β in gout and pseudogout has been confirmed by the efficacy of blocking agents against IL-1 signaling." (PMID 35628185, 2022). "A recent study of the biological mechanism supporting the association between excessive food intake and the onset of gout demonstrated a synergistic relationship between free fatty acids (FFA) and MSU for IL-1β activation." (PMID 35370689, 2022). "P2X7R has attracted widespread interest as a therapeutic target for gout, as it mediates IL-1β release in response toATP." (PMID 36052144, 2022). "Neutrophils correlate with the elevation of IL-1β, IL-8, and TNF-α levels, which are necessary cytokines in inflammation and significant mediators implicated in the pathogenesis of gout." (PMID 36286462, 2022). "Strong evidence for the role of IL-1β in gout-related pain and inflammation is provided in animal and human studies." (PMID 35370689, 2022). "First, IL-1β, highly expressed in severe equine asthma, has been demonstrated to induce NETs release in mouse models of gouty arthritis and abdominal aortic aneurysms." (PMID 35911691, 2022). "Uric acid crystals can activate NLRP3 inflammasomes and trigger IL-1β secretion, suggesting that inflammasome activation and IL-1β secretion are the driving factors of gout." (PMID 35656105, 2022). "It is also known that several polymorphisms in inflammasome-related genes (NLRP3, IL-1β, CARD8) are associated with a greater risk of developing gout." (PMID 35629398, 2022).
gout (continued). "Recent studies have shown that interleukin-1β (IL-1β) is a major regulatory inflammatory cytokine of gout, promoting neutrophil influx into the synovial membrane and joint fluid, which is a pathological hallmark of acute inflammatory attacks." (PMID 35370689, 2022). "It is important to note that neutrophils are the main cells present in gout synovial fluid in humans and that IL-1β is the key cytokine driving the inflammatory process of an acute gout attack." (PMID 36173505, 2022). "For instance, bioactive tissue factor (TF) was detected on NETs in vein and arterial thrombosis and mature interleukin-1 beta (IL-1β) in Familial Mediterranean Fever and gouty arthritis." (PMID 36555464, 2022). "The release of biologically active IL-1β in gout requires two steps: initiation and activation, a biological process that occurs mainly in macrophages." (PMID 36052144, 2022). "As a clinical drug for gouty arthritis treatment, colchicine (COL) can suppress the activation of caspase-1 and prevent the release of IL-1β and IL-18, thereby inhibiting the occurrence of gouty arthritis." (PMID 36297105, 2022). "Effects of total extract of Lagotis brachystachya on serum TNF-α, IL-1β, and IL-6 of rats with chronic alcoholic liver injury and gouty arthritis (x ± s, n = 8)." (PMID 36176434, 2022). "rhPRG4 reduced phagocytic activation of gout monocytes both under basal and primed conditions and this reduction resulted in a downstream attenuation of IL-1β secretion, and rhPRG4’s efficacy was equivalent to a clinically approved biologic, IL-1RA." (PMID 34992596, 2021). "It is essential to explore the mechanism of activation of IL-1β for investigating the pathogenesis of gout flares, and it is found that the purinergic signaling pathway is involved in the regulation of IL-1β secretion in gout." (PMID 34925366, 2021). "Uric acid crystals can activate the NLRP3 inflammasome and trigger IL-1β secretion, suggesting that inflammasome activation and IL-1β secretion are the driving factors behind the occurrence of gout." (PMID 33677475, 2021). "TSD also has remarkable anti-inflammatory and analgesic effects, which can inhibit the expression of the cytokine IL-1β and obviously improve histopathological lesions in gouty arthritis." (PMID 34721647, 2021). "In this line, β-carotene administered orally (30 mg/kg) inhibited NLRP3 inflammasome activation in a model of gouty arthritis in mice, as well as suppressed levels of IL-1β in synovial fluid cells isolated from gout patients." (PMID 34677429, 2021). "NLRP3 inflammasome activation and the release of IL-1β have essential roles in gout by triggering acute gout flares." (PMID 33534121, 2021). "IL-1β and other interleukins (IL-6, IL-8) attract neutrophils to the site of inflammation resulting in an acute gout flare." (PMID 34246297, 2021). "Immediately after the release of IL-1β, the inflammatory cascade response induces neutrophil accumulation in the joints, thus, exacerbating gout flare." (PMID 34925366, 2021). "The enhanced production of mature IL-1β by gout PBMCs was shown to likely be due to enhanced caspase-1 mediated conversion of pro-IL-1β." (PMID 34992596, 2021). "In an acute gout mouse model, oral administration of TF to mice effectively alleviated paw edema, reduced inflammatory features, and decreased the levels of IL-1β in mouse foot tissue." (PMID 34079466, 2021). "We have previously reported that IL‐38 can inhibit IL‐1β, IL‐6, and KC in a model of gouty arthritis." (PMID 33620105, 2021). "Recently, an animal experiment showed that colchicine (a common drug for gout) on macrophage in a mouse brain inhibits the RAS gene family with the inhibition of IL-1β (Interleukin 1 beta)." (PMID 34502281, 2021). "Damage-associated molecular patterns (DAMPs) can also activate the NLRP3 inflammasome in gout and increase IL-1β gene expression via activation of toll-like receptors 2 and 4 (TLR2 and TLR4)." (PMID 34992596, 2021).
gout (continued). "Based on these observations, IL-1β blockers are considered promising candidates for the therapy of gout." (PMID 33746978, 2021). "Next, we tested the possibility that CIRP acts as a priming stimulus using a model of gouty arthritis, in which uric acid induces IL-1β secretion." (PMID 33902703, 2021). "Loganin reduced the production of mature IL-1β and IL-18 in macrophages and gout tissues stimulated with MSU crystals." (PMID 33670601, 2021). "Further autoinflammatory aspects of gout are the typically self-limiting nature of acute flares and the central role of inflammatory cytokines, such as interleukin (IL)-1β, suggesting that pro- and anti-inflammatory regulatory pathways are involved in gout." (PMID 33926105, 2021). "Active caspase-1 catalyzes the conversion of pro-interleukin-1 beta (pro-IL-1β) to mature IL-1β, which is the primary effector pro-inflammatory cytokine in gout." (PMID 34992596, 2021). "In fact, in a MSU-induced gout model, rats fed on a ketogenic diet showed reduced IL-1β serum levels and intra-articular exudate and synovial inflammation were less severe." (PMID 34829842, 2021). "An acute gout flare is conditioned not only on activation of NLRP3 inflammasomes but also on upregulation of IL1B transcription." (PMID 34246297, 2021). "Recognition of the importance of NLRP3 inflammasome activation and bioactive IL-1β release in the initiation of gout flares has led to the development of antiIL-1β biological therapy for gout flares." (PMID 34721647, 2021). "IL-1β is an important inflammatory mediator of gouty arthritis, which is mainly produced through the TLR4-NF-κB and NLRP3 inflammasome signaling pathways." (PMID 33935726, 2021). "Accumulating studies have shown that TNF-α and IL-1β are closely related to the pathogenesis of gouty arthritis." (PMID 34803702, 2021). "Undoubtedly, IL-1β plays a pivotal role in gout; however, increasing evidence suggests other IL-1 family members can be involved in gout." (PMID 33926105, 2021). "Enhanced phagocytic activation of gout monocytes under basal conditions (p<0.001) was associated with ROS generation and MSU stimulated IL-1β secretion (p<0.05)." (PMID 34992596, 2021). "The release of IL-1β as a key regulatory proinflammatory cytokine in gout cases has been shown to promote the influx of neutrophils into the synovium and joint fluid, which is a pathological hallmark of an acute inflammatory attack." (PMID 34577821, 2021). "In gout, fever can be present mostly when there is a polyarticular involvement, since the final production of IL-1β can be a possible trigger for fever in patients affected by crystal arthropathies." (PMID 33926105, 2021). "Macrophages intake MSU crystals, the trigger for NLRP3 inflammasome activation, which leads to the release of interleukin (IL)-1β and results in the flaring of gout." (PMID 34440688, 2021). "For this reason, targeting inflammasome and IL-1β has become crucial in treating the inflammatory component of gout." (PMID 33926105, 2021). "The activation of NLRP3 inflammasome and subsequent induction of the release of IL-1β exerts a central role in the initiation of gout flares." (PMID 34925366, 2021). "The results clearly showed that SHA treatment suppressed the major inflammatory cytokines (TNF-α and IL-1β), which are essential in the initiation and progression of gouty arthritis." (PMID 34284768, 2021). "APOA1 can bind MSU crystals and/or inhibit IL-1β production, having thus a role in initiation and/or resolution of gout attacks." (PMID 33926105, 2021). "Consistently, two previous studies presented similar results showing that luteolin and luteolin-4′-O-glucoside, a structural analog of luteoloside, decreased serum TNF-α and IL-1β concentrations in MSU crystal-induced gouty arthritis." (PMID 34803702, 2021). "Because the proinflammatory cytokine IL-1β is crucial for inflammation, as well as in acute gouty arthritis, there have been several studies addressing its regulation by miRNAs." (PMID 34246297, 2021).
gout (continued). "Gene is downregulated in association with promoter hypermethylation, Here, hypermethylation of BIRC2 likely suppressed BIRC2 expression and increased IL-1β production, exacerbating gout." (PMID 33493135, 2021). "As one of the prototypes of IL-1β driven auto-inflammatory diseases, gouty arthritis clinically results from an excessive formation of acid uric crystals, especially in the joints of the toes." (PMID 34830435, 2021). "Loganin inhibited MSU crystals-induced secretion of inflammatory cytokines such as IL-1β and IL-18, resulting in the suppression of gout inflammation in tissues injected with MSU crystals." (PMID 33670601, 2021). "One study also found that the ethanol extract of P. igniarius can inhibit XO activity and relieve acute gout inflammation by down-regulating the expression of IL-1β and ICAM-1 in vitro." (PMID 35087407, 2021). "Interleukin (IL)-1β has been reported to have an important role in MSU-induced inflammation in gout." (PMID 35095497, 2021). "The expression of IL-1β and IL-18 was increased in the peripheral blood mononuclear cells of patients with active gout." (PMID 34830282, 2021). "rhPRG4 reduced bead phagocytosis by normal and gout monocytes compared to IL-1RA and both treatments were efficacious in reducing IL-1β secretion (p<0.05)." (PMID 34992596, 2021). "The mean reduction in IL-1β (95% CI) in the gout cohort was 27.3% (15.2%-39.4%) with IL-1RA and 30.9% (21.1%-40.6%) with rhPRG4." (PMID 34992596, 2021). "MSU crystals induce the activation of the NLRP3 inflammasome and subsequent release of mature IL-1β, contributing to the development and progress of gouty arthritis." (PMID 33670601, 2021). "Although IL-1β has been identified as a key mediator, the stimulus that primes the inflammasome cascade in a sterile inflammatory arthritis, gout, is unclear." (PMID 33902703, 2021). "In gout PBMCs with IL-1β secretion < 500 pg/mL, IL-1RA and rhPRG4 treatments showed no significant reductions in IL-1β release (p>0.05)." (PMID 34992596, 2021). "A possible explanation for the enhanced generation of mature IL-1β by gout PBMCs is chronic hyperuricemia where uric acid priming enhances IL-1β secretion by human PBMCs, via activating the AKT-PRAS40 autophagy pathway." (PMID 34992596, 2021). "The activation of NLRP3 inflammasome releases large amounts of IL-1β is a central process of MSU-mediated gout flares." (PMID 34925366, 2021). "These successfully confirmed that TF and AM had good effects on acute gouty arthritis by reducing foot thickness, IL-1β level, and lymphocyte infiltration." (PMID 34079466, 2021). "Studies have shown that gout caused by urate was mediated by the TLR4/NF-κB signaling pathway, and the IL-1β released was linearly related to it." (PMID 34552978, 2021). "In this study, we focused on how uric acid induces pro-IL-1β processing in innate immune cells and thus contributes to the development of gout." (PMID 33902703, 2021). "This information, together with the observation of neutrophil invasions around the uric acid crystals in gouty arthritis, suggests that neutrophils function as danger sensing cells that contribute to the production of biologically active IL-1β." (PMID 33902703, 2021). "A linkage between gout incidence and polymorphisms has been reported in PPARGC1B, which increased NLRP3 and IL-1β expression." (PMID 33926105, 2021). "Recent studies suggest that inflammasome activation and the subsequent IL-1β production play an import role in gouty arthritis." (PMID 33902703, 2021). "IL-1RA and rhPRG4 treatments reduced IL-1β secretion by gout PBMC specimens that exhibited high urate crystal stimulated IL-1β release (>500 pg/mL) (p<0.01; p<0.001)." (PMID 34992596, 2021). "Activation of NLRP3 inflammasome promotes MSU crystal-induced inflammation in macrophages, while its inactivation averts gout by reducing the production of IL-1β." (PMID 33505510, 2021).